EGFR (epidermal growth factor receptor)
Diseases named in the same sentence as EGFR in open-access papers (continued):
Sharing a sentence is not in itself a finding about the gene and the disease.
tumor (continued). "HKB99 is also active against EGFR-specific low molecular erlotinib-resistant tumor cells, emphasizing the importance of PGAM1 inhibitors such as HKB99 for a tumor-therapeutic agent." (PMID 36077431, 2022). "Many studies have shown that METTL3 promotes tumor growth and aggressiveness by regulating the mRNA decay and stability or mRNA translation of numerous tumor-associated genes, such as SOCS2, BATF2, EGFR, TAZ, MAPKAPK2, and DNMT3A." (PMID 35456475, 2022). "Another chemokine that has been linked to EGFR signalling is CCL21, previously shown to be involved in the recruitment and infiltration of tumour-specific T-cells into the TME." (PMID 36010935, 2022). "Subsequent longitudinal 2D BLI imaging demonstrated an accumulation of EGFR CAR T cells ± IL-2 at the tumor site in the following two weeks, while control-treated animals exhibited a signal in an area attributable to the spleen in dorsal and ventral view." (PMID 35836798, 2022). "Afatinib significantly attenuated both the growth and size of tumor nodules in the xenograft mouse model of p.L747P compared to other EGFR TKIs (P<0.001)." (PMID 35223527, 2022). "NPs conjugated to EGFR-targeting antibodies or loaded with EGFR inhibitors have been increasingly studied in recent years with the aim of enhancing tumor-specific delivery and inhibition." (PMID 35890738, 2022). "Epidermal growth factor receptor (EGFR) was found to be overexpressed in NB tumor specimens, and its signaling was found to be dysregulated in multi-drug resistant NB cell lines." (PMID 35563171, 2022). "Identified by next-generation sequencing (NGS), EGFR G724S was found from a primary and a secondary tumor biopsy, respectively." (PMID 36505860, 2022). "The epidermal growth factor receptor (EGFR) signaling pathway plays a critical role in tumorigenesis and tumor progression." (PMID 36358752, 2022). "To investigate the requirement of EGFR activation for aerotaxis, we first verified its expression by immunofluorescence (IF) in a selection of tumour cells." (PMID 36380366, 2022). "The proportion of CXLC10-expressed tumor cells among persistent tumor cells was increased according to EGFR-TKI treatment." (PMID 36612121, 2022). "In the present study, we demonstrated that the recombinant fusion protein Fv-LDP-D3 has high affinity for EGFR-overexpressing EC cells, ensuring localization to the tumor and reducing toxicity to normal cells." (PMID 35416106, 2022). "The favorable safety profile and promising anti-tumor activity of the dual-function JAK3-ERBB1/EGFR inhibitor WHI-P131 also warrants further studies." (PMID 36311273, 2022). "The presence of an EGFR-mutant tumor was negatively correlated with DFS, although this correlation was not significant." (PMID 35740676, 2022). "Nevertheless, we have identified a pEGFR-positive NSCLC tumor (patient 10) with a 0.99 gefitinib-treatment score, which showed a 98% reduction in Ki67 levels upon EGFRi, thus suggesting dependency on EGFR to sustain viability." (PMID 36494469, 2022). "Here, we report an application of aptamers to enhancing specificity in imaging tumor cells bearing the epidermal growth factor receptor (EGFR)." (PMID 36615487, 2022). "We demonstrated that the current anti-EGFR antibody treatment dose can probably be significantly lowered for this purpose since diluted patient plasma was sufficient to completely opsonize tumor cells and induce efficient ADCP." (PMID 35035479, 2022). "Step 2: Reproduce the tumor volume evolution of human EGFR+ LUAD tumor cells transplanted into immunocompromised mice." (PMID 35796890, 2022). "ORR in EGFR T790M-negative and -positive patients were 52% and 9%, respectively, suggesting beneficial anti-tumor activity." (PMID 36551608, 2022).
tumor (continued). "EMT was reported as a mechanism of resistance to TKIs, with EMT identified in 2 of 37 (i.e., 5%) patients in tumor specimens obtained after EGFR treatment and SCLC transformation." (PMID 35209919, 2022). "All the target compounds were tested for inhibitory effects against wild type EGFR (EGFRwt) and three tumour cells, including A549, PC-3, and HepG2." (PMID 35260020, 2022). "EGFR expression would provide information about tumor aggressiveness while TIL marker(s) expression would give some input regarding the tumor immune microenvironment and overall prognosis." (PMID 35957892, 2022). "Our results support the plausibility for ST6Gal-I directly influencing EGFR signaling to regulate cell mechanics, another key element regulating tumor cell response to the microenvironment." (PMID 35157848, 2022). "CRISPRi screening revealed multiple newly acquired interactive enhancers, including two adjacent upstream enhancers, all of which had a strong positive effect on the activity of EGFR-amplified tumor cells." (PMID 35494014, 2022). "Tyrosine kinase inhibitors such as gefitinib and erlotinib have shown efficacy in tumours with EGFR exon amplification." (PMID 36267410, 2022). "Overexpression of EGFR in many tumor types provides a basis for the design of therapies that use EGFR as a decoy to guide effectors of the adaptive or innate immune systems to EGFR-expressing cancers and to destroy EGFR-expressing cancer cells." (PMID 36185288, 2022). "Epidermal growth factor receptor (EGFR)‐tyrosine kinase inhibitors (TKIs) are important milestones in the development of tumor‐targeted therapy and have greatly improved outcomes for NSCLC patients." (PMID 34958168, 2022). "In GBM cells, Ras mutations are not frequent; nevertheless, the Ras pathway is often activated by the overexpression of tyrosine-kinase receptors such as EGFR, which is common in this tumor." (PMID 35897776, 2022). "In this study, we aimed to investigate the effects of adipose-derived mesenchymal stem cells secreted exosomes on the expression of aquaporin 5 and EGFR genes in the HCT-116 tumor cell line." (PMID 36114463, 2022). "Several studies have shown that expressing particular proteins on the surface of exosomes can target them to tumor cells expressing EGFR." (PMID 36304147, 2022). "The protein complexes that were of significant interest to this study were the Heat Shock Protein (HSP) and Epidermal Growth Factor Receptor (EGFR) family members which were noted to be aberrant between the pairs of normal and tumour colon tissues." (PMID 36499558, 2022). "In concordance with a role for the tumor microenvironment and the EGFR pathway more specifically, our group reported that the strong activation of EGFR by EGF resulted in EMT induction with an up‐regulation of SNAIL, SLUG, and ZEB1." (PMID 34382739, 2022). "As preclinical models, the authors used cell lines overexpressing EGFR or FAP to mimic tumor and microenvironment cells, respectively, in different coculture ratios to validate the specificity of the different formulations." (PMID 35626078, 2022). "Co-inhibition of both EZH2 and EGFR elicited a synergic effect on tumor growth suppression in CRC by triggering autophagy and inducing apoptosis." (PMID 35449124, 2022). "The results of these trials are eagerly awaited to determine the impact of combination mAb and TKI therapy on EGFR Ex20ins tumours." (PMID 35053553, 2022). "c.1799T>A is linked to worse prognosis and resistance to standard therapies in CRC (e.g., EGFR inhibitors) and indicates tumor aggressiveness." (PMID 35723313, 2022). "As a companion diagnostic, the Guardant360 CDx liquid biopsy test was granted FDA approval alongside amivantamab to detect the presence of EGFR exon 20 insertions in circulating tumor DNA." (PMID 34913823, 2022).
tumor (continued). "Preclinical data suggest that EGFR inhibition by cetuximab is accompanied by several potentially relevant immune effects, including reduction in PD-L1 expression and induction of tumor cell recognition via major histocompatibility complex (MHC)." (PMID 35346313, 2022). "From this point of view, the investigation of ICD will provide new approaches for tumor treatment in EGFR-mutant NSCLC." (PMID 35935943, 2022). "ALDH1A1 maintains self‐renewal of CrT/TICs and facilitates the expression and secretion of EGF from CrT/TICs, which subsequently promotes the activation of EGFR signalling in differentiated cancer cells and tumour growth of LUSC." (PMID 36504325, 2022). "The need for novel therapeutic approaches has emerged to circumvent shortcomings related to acquired resistance and on-target off-tumor toxicities induced by EGFR TKIs and anti-EGFR antibodies." (PMID 36185288, 2022). "The organoid response to EGFR-targeted PDT proved to be donor-dependent and tumor-specific, while induction of EGFR expression increased sensitivity to EGFR-targeted PDT." (PMID 35213974, 2022). "Cetuximab binds to the epidermal growth factor receptor on tumor cells but promotes the growth of immunosuppressive regulatory T cells in the tumor microenvironment." (PMID 35132165, 2022). "For this reason, P6 and P9 were selected for additional studies as drug carriers for the selective elimination of the EGFR expression tumor." (PMID 35890400, 2022). "The EGFR overexpression contributes to the highly proliferative and treatment-resistant nature of this tumor." (PMID 36199696, 2022). "For example, gefitinib, an EGFR inhibitor suppressing tumor growth and angiogenesis, was recently shown to inhibit the crosstalk between macrophages and cancer cells by blocking receptor interacting protein kinase 2 (RIPK2)." (PMID 35140725, 2022). "Overall, these data provide strong evidence that 3l suppresses CDX tumor growth in ESCC in vivo, the effect was associated with its inhibition of EGFR signaling." (PMID 36467103, 2022). "This indicates that the CTX-INS-GNPs indeed targeted EGFR-expressing tumor cells, which enabled total elimination of these cells." (PMID 36324626, 2022). "EGFR has been proved to be abnormally or highly expressed in many solid tumors and can regulate various biological activities of tumor cells, which inhibit apoptosis through its downstream signal transduction." (PMID 36685887, 2022). "In particular, anti-EGFR immunoviroplexes exhibited the most efficient siRNA transfection into tumor cells, resulting in significant inhibition of tumor growth." (PMID 36499115, 2022). "Inversely, EGFR degradation or inactivation leads to the ferroptosis of tumor cells via activating NRF2." (PMID 35692844, 2022). "The inhibition of these genes (dual EGFR/MEK and/or mTOR) resulted in a better response in tumor models exhibiting RAS family, BRAF or PIK3CA mutations." (PMID 36556139, 2022). "The chemotherapeutic resistance-related genes (mainly AKT1 and ERBB1) and EGFR tyrosine kinase inhibitor-related genes were decreased in the effective group, and multiple tumor driver genes (mainly Myc) were increased in the ineffective group." (PMID 36230574, 2022). "Although it has been demonstrated that the deletion of EGFR transiently reduces KRAS-mutant tumor growth, EGFR therapies trigger tumor escape mechanisms involving non-EGFR ERBB family members." (PMID 35740503, 2022). "Mechanistically, EGF secreted by TAMs induced EGFR+ tumor cell migration and TAM spheroid formation through VEGF-C/VEGFR3 signaling." (PMID 35682890, 2022). "The interplay of cellular expression, tumor cell density, and distribution pattern led to the scale-dependent nature of EGFR expression." (PMID 35332092, 2022).
tumor (continued). "The decreased expression of EGFR on the normal epithelium such as the skin and gastrointestinal tract results in on-target/off-tumor toxicity and lowers the dose of ITs available to target tumors, contributing to challenges in its applicability." (PMID 36555466, 2022). "Preliminary results from a phase II clinical trial (NCT04036682) evaluating TAS6417 in a cohort of 37 NSCLC patients with EGFR Ex20ins previously treated with platinum-based therapy showed an acceptable safety profile and encouraging anti-tumour activity." (PMID 35053553, 2022). "EGFR autocrine pathway is involved in tumor development and progression activities, including angiogenesis, cell growth, and metastasis." (PMID 36080304, 2022). "In particular, EGFR‐targeted immRNA‐loaded RBCEVs showed greater tumour suppression in the lungs, an effect attributed to the increased immRNA delivery to tumour cells in this treatment." (PMID 35430766, 2022). "Generally, FOXF2 and EGFR are associated with proliferation and anti-apoptosis in cancer, showing that the FOXF2 gene plays a critical role in tumor suppression." (PMID 35164166, 2022). "According to longitudinal studies, certain driver co-alterations had already been detected in patients’ ctDNA samples before the EGFR-TKIs initiation, indicating the spatial tumor heterogeneity." (PMID 35884398, 2022). "The corresponding PDXs mirrored patient tumor sensitivity to anti-EGFR treatment, and the tumor response of PDX_489 and PDX_545 were mCR (−100.00%) and mPD (352.76%), respectively." (PMID 35260570, 2022). "This Anti-EGFR enhanced the cellular absorption in vitro and in vivo in experimental mice with tumor volume about 80–100 mm3 developed using A549 cells." (PMID 36085575, 2022). "By leveraging the tumor-driving EGFR/K-RAS/SIAH pathway activation (ON)/inactivation (OFF) in TNBC, we hope to differentiate TNBC pIR patients by correlating SIAHHigh (high-risk) versus SIAHLow (low-risk) expression in residual tumors post-NACT/NST." (PMID 36176751, 2022). "Exogenous EGFR rescued impaired abilities of tumor spheres formation and colony formation mediated by sh-EGFR, and spheroid tumor cells were insensitive to erastin-induced ferroptosis." (PMID 35725558, 2022). "This study investigated EGFR-induced epithelial-to-mesenchymal transition (EMT) as a central parameter in tumor progression and identified novel prognostic and therapeutic targets, and a candidate predictive marker for EGFR therapy response." (PMID 36076232, 2022). "There was a slight change in serological markers before and after switching to aumolertinib, which indicated that the third-generation EGFR-TKIs performed excellently as anti-tumor medicines." (PMID 35677717, 2022). "It was suggested that the low efficacy of ICIs in EGFR-mutant NSCLC was related to the specific TME, tumor mutation load (TMB) and PD-L1 expression level." (PMID 35935943, 2022). "Collectively, these data showed that NK1R interacted with EGFR and that EGFR played key role in NK1R-mediated tumor cell proliferation and migration in NSCLC." (PMID 35013118, 2022). "Critically, it is important to understand the interaction between tumor cells and the tumor microenvironment in anti-EGFR therapy resistance." (PMID 33632198, 2021). "Radiosensitizing by cetuximab therefore affects the EGFR-function by slowing down DNA repair and enhancing reproductive cell death in tumor cells." (PMID 34321039, 2021). "Our results suggest the decreased PCr/Pi ratio in patients with EGFR amplified or MGMT methylated tumor." (PMID 34298788, 2021). "EGFR can contribute to transformation of cellular phenotypes that enable tumor cell growth and survival." (PMID 33925065, 2021). "Conversely, the expression of VEGF-A and EGFR was significantly higher only in IR/Ipsi-tumor group compared to the other groups." (PMID 34764346, 2021). "It was previously established that constitutive EGFR and NF-κB activities play a critical role in tumor development." (PMID 34769306, 2021).
tumor (continued). "Almost half of the patients carry EGFR-driven tumor with phosphatase and tensin homolog (PTEN) deletion, which are resistant to EGFR target therapy, implying PTEN deficiency plays an important role in resistance to anti-EGFR therapy." (PMID 34925034, 2021). "Several studies have confirmed that EGFR mutations in NSCLC are closely related to an immunosuppressive tumour microenvironment (TME) and a lower tumour mutation burden (TMB), which are responsible for an inferior response to PD-1 blockade in NSCLC." (PMID 34631565, 2021). "Since the gene encoding IL-26 is absent in mice, we utilized human IL-26 transgenic (hIL-26Tg) mice as a tumor-bearing murine model to characterize the role of IL-26 in the differential effect of EGFR-TKI in human and mice and to confirm our in vitro findings." (PMID 34021125, 2021). "MiRNAs regulates anti-EGFR drug resistance by directly targeting tumor-related genes involved in EGFR-related signaling pathways in CRC." (PMID 35111681, 2021). "There are both suppressor genes and tumor oncogenes mutated in all nine/nine parts of the tumor, such as EP300 and NCOR2 (NOTCH), PTEN (PI3K), EGFR (RTK-RAS) and FAT1 (Hippo)." (PMID 33922652, 2021). "As autophagic adaptor p62 can induce genomic instability and tumor progression in some contexts, we studied the function of p62 in EGFR‐TKI‐resistant PC9/GR cells." (PMID 33486901, 2021). "In fact, it was demonstrated that inhibition of EGFR activation in tumor cells leads to activation of a β1 integrin pathway that promotes migration, undermining EGFR blockade." (PMID 32280996, 2021). "Targeted sequencing was performed on paired CSF and blood samples collected at LM diagnosis from patients with either EGFR exon 19 deletion (19del) (n = 19) or EGFR exon 21 L858R (n = 26) detected from their tumor samples at baseline (before developing LM)." (PMID 35127465, 2021). "A human tumor microarray analysis demonstrated that TNBC tumors express EGFR and co-express BCL-xL or both BCL-xL and BCL2." (PMID 34207383, 2021). "The loss of BRG1 is specific to the progression of an EFGR wild-type NSCLC tumor as compared to an EGFR mutant tumor even so, the pathogenesis of it is still being investigated." (PMID 34440689, 2021). "All tumor responses were observed in the 350 mg group, with 10 of them having EGFR overexpression and 4 having EGFR amplification." (PMID 34688250, 2021). "Studies have already indicated that EGFR‐mediated RAS/RAF/MEK/ERK signalling pathway plays a critical role in the induction of autophagy in various tumours." (PMID 33960631, 2021). "Clinically, re‐administration of the same chemotherapeutics, including platinum agents and EGFR TKIs, has shown promising effects after a ‘drug holiday’ with tumour progression." (PMID 34709767, 2021). "They demonstrate that decorin acts as a tumor suppressor in cancer cells and human xenograft mouse models by destabilizing the E-cadherin-EGFR signaling axis, and their findings suggest potential therapeutic strategies for this aggressive breast cancer." (PMID 33452400, 2021). "Another miRNA with tumor-suppressive functions that act on EGFR membrane turnover and downstream AKT/ERK pathway is miR-1272." (PMID 33805590, 2021). "Western blot analysis of these drug-treated PDXs demonstrated that the blockade of the EGF signaling pathway was associated with a decrease in the p-EGFR level and reduction in PDX tumor size." (PMID 34204797, 2021). "In genetically engineered mouse models (GEMMs), EGFR-driven tumors express higher levels of PD-L1 with a more immunosuppressive tumor microenvironment (increased FoxP3+ T-cells, decreased CD8+/CD4+ ratio)." (PMID 34488906, 2021). "The pretreatment with miR-145 reduced tumor growth by suppressing the expression of EGFR induced cell arrest of the G1/S cycle phase, and improved the sensitivity of A549, NSCLC cell line, to erlotinib." (PMID 34830377, 2021).